FAT4 (FAT atypical cadherin 4)
Diseases named in the same sentence as FAT4 in open-access papers (continued):
Sharing a sentence is not in itself a finding about the gene and the disease.
tumor (continued). "Therefore, combinatorial effects of reduced FAT4 gene expression and other factors could be necessary for tumor transformation in MCF-10A cells." (PMID 25679223, 2015). "Many of these genes, including tumor suppressors such as CDKN2A, HLA-A, and FAT4, have established roles in hematolymphoid malignancies." (PMID 41008837, 2025). "The tumour volume of the UBE4B knockdown group was significantly smaller than that of the corresponding control group, and the tumour volume of the UBE4B and FAT4 co-knockdown group was significantly larger than that of the group with UBE4B knockdown alone." (PMID 40701960, 2025). "In particular, FAT4 silencing in ALCL cells activated the β-catenin and YAP1 pathways, which play crucial roles in tumor growth, and conferred resistance to chemotherapy." (PMID 39478125, 2024). "The results indicated that FAT4 expression decreased gradually following the tumor diameter, and that lymph nodes metastasis in the TCGA LUAD cohort were related to both mRNA and protein expression of FAT4." (PMID 35770846, 2023). "We found that treatment with YFJDT increased FAT4 accompanied by the increase of apoptosis and autophagy and inhibition of EMT, both in tumor-bearing mice and in A549 cells, similar to the previous finding." (PMID 35132327, 2022). "FAT4 has been shown to inhibit epithelial to mesenchymal transition (EMT) and to act as a tumor suppressor." (PMID 35132327, 2022). "In contrast, mutant BRAF, ATM, LRP1B, FAT4, FMN2, TRRAP, and ROS1 had higher stromal score (except ATM), immune score and ESTIMATE score, and the tumor purity was lower than the wild-type." (PMID 33836681, 2021). "Nevertheless, our germline analysis identified four genes with known functions likely to contribute to tumor progression and potentially drug response: FAT1 and FAT3, FAT4, and ERCC2, modeled by targeting kug, ft, and xpd, respectively." (PMID 33733072, 2021). "The results of these experiments should provide novel insights into the effects of FAT4 and PI3K/AKT signaling on tumor therapy." (PMID 30832706, 2019). "Further, we have shown that in particular tumours, for PTEN, CDK12 and FAT4, this miRNA or methylation-based suppression happens independently of other gene regulatory factors, such as mutations and copy number changes." (PMID 30531873, 2018). "We treated GC tumor cell lines AGS, MKN-28 and MKN-45 with 1μM of 5-aza-2’-deoxycytidine (5-Aza-dC) for 48h and demonstrated increased expression of FAT4 mRNA." (PMID 29435168, 2018). "Further, across multiple cancer types, three key tumour suppressor genes, PTEN, FAT4 and CDK12, consistently tended towards exclusivity in their regulation, lending support for the importance of miRNA-based regulation of these genes." (PMID 30531873, 2018). "The mouse Fat4 gene is inactivated owing to LOH and promoter CpG hypermethylation in subcutaneous tumor induced by Cre/LoxP-mediated random chromosomal deletion." (PMID 23076869, 2012).
tumor (continued). "In addition, the tumour weight of the UBE4B knockdown group was lower than that of the control group, and the tumour volume of the UBE4B and FAT4 co-knockdown group was significantly larger than that of the UBE4B knockdown group." (PMID 40701960, 2025). "FAT4 (GA + PA vs. Sham + PA, GDA + PA vs. Sham + PA, and GDA + PA vs. Placebo + PA) and FAT1 (GA + PA vs. Sham + PA and GA + PA vs. Placebo + PA) were the top increased tumor suppressors based on FDR." (PMID 39409043, 2024). "While FAT4 has been documented in several cancers of its suppressor role, the function of FAT4 in tumor immunity has not been investigated." (PMID 35770846, 2023). "Therefore, xCells data was applied to validate the relationship between FAT4 expression and the immune components, which include 64 immune cell types profiles in LUAD, and analyzed the proportion of tumor‐infiltrating immune subtypes." (PMID 35770846, 2023). "The FAT4 gene belongs to the FAT family and is a tumor suppressor." (PMID 35132327, 2022). "Here, we show that transient Src activation represses FAT4 mRNA expression and leads to tumor transformation in MCF-10A cells, which are immortalized normal human mammary epithelial cells." (PMID 25679223, 2015). "Moreover, FAT4 expression was negatively correlated with DNA repair, MYC targets, G2M checkpoint, DNA replication, reactive oxygen species-upregulated genes, cellular response to hypoxia, and tumor proliferation signature." (PMID 37735184, 2023). "To investigate the mechanism of FAT4 overexpression activates antitumor immunity, we proceeded to construct subcutaneous graft tumors in immunocompetent C57BL/6 mice and collected tumors for further analysis before tumor regression (2 weeks after local injection)." (PMID 37658376, 2023). "In this section, we demonstrate that FAT4 overexpression prevented tumor progression in immunodeficient mice, increased CTL activity, and even promoted tumor regression in C57BL/6 immunoreactive mice, suggesting that an intact immune system enhances the antitumor efficacy of FAT4 overexpression." (PMID 37658376, 2023). "FAT4 mRNA levels were lower in GC tumor samples than adjacent noncancerous tissues." (PMID 29435168, 2018). "Indeed, among the most upregulated genes in FAT4 knockdown cells we found ARHGEF6, encoding for the guanine nucleotide exchange factor αPIX that activates Rac1 and Cdc42 GTPases and ARHGDIB, a negative modulator of the RhoA tumor suppressor." (PMID 39478125, 2024). "Additionally, nearly all cancer-associated Fat4 and Dchs1 mutations in the COSMIC database are located outside of the binding interface, suggesting that the tumor suppressor role of Fat and Dachsous may not require their direct interactions." (PMID 36797229, 2023). "Notably for FAT4, BFAR, CRB2, and PEX14, we did not identify somatic mutations in the wild-type allele of these genes in the cases carrying germline mutations, suggesting that if they are contributing to tumor formation, they most likely do not function as classical tumor suppressors." (PMID 31101826, 2019). "By analyzing the relationship between the expression level of FAT4 in tumor tissues and tumor stage, we found with the increase of AJCC stage of KIRC tumor, the down-regulation of FAT4 increased, it suggesting a negative correlation between FAT4 and AJCC stage." (PMID 36051999, 2022).
cancer (78 papers, 2012 to 2026). A tumor composed of atypical neoplastic, often pleomorphic cells that invade other tissues. "With regards to germline variants, FAT4 was the most frequently mutated gene within our preselected gene panel and is also associated with several cancers." (PMID 39492681, 2025). "Fat4 has also been classified as a tumor suppressor protein, as loss-of-function mutations and gene suppression are associated with increased cancer cell proliferation, invasiveness, and metastasis." (PMID 36797229, 2023). "We observed a statistically positive correlation between cancer-associated fibroblasts and FAT4 expression in most tumors." (PMID 36051999, 2022). "FAT1 and FAT4 have been reported to be frequently mutated in gingivo-buccal OSCCs in an Indian cohort and are associated with tumorigenesis in various cancers including HNSCC." (PMID 34136393, 2021). "The co‐occurred mutations in RNF43 and FAT3/FAT4 disrupted the Wnt signaling and thus promoted the development of cancer." (PMID 30107644, 2018). "Altogether, these results propose a novel mechanism by which actin dynamics regulate cancer-related traits through the loss of FAT4-mediated cell-cell adhesion." (PMID 25679223, 2015). "Indeed, a search in TCGA database showed that FAT4 is commonly down-regulated in several cancers and lower expression levels of FAT4 are significantly associated with worse OS in various tumors." (PMID 39478125, 2024). "In particular, FAT4 is frequently mutated or downregulated in several types of human cancer." (PMID 39478125, 2024). "Then, we further detected the mutation of FAT4 in multi‐kinds of cancer." (PMID 35770846, 2023). "Low FAT4 expression during cancer metastasis was associated with decreased survival." (PMID 29435168, 2018). "An across database survey revealed that FAT4 was mutated or deleted in various human cancers." (PMID 26672766, 2016). "Importantly, it is known that 10% of somatically mutated genes can confer susceptibility to cancer when mutated at germline level, so FAT4 could be an interesting candidate gene." (PMID 33525650, 2021). "However, the molecular mechanisms underlying the down-regulation of FAT4 gene expression in human cancers remain unknown." (PMID 25679223, 2015). "Based on the results of the pancancer analysis, FAT4 has been recognized as a novel prognostic biomarker for various cancers." (PMID 40701960, 2025). "Genes such as PIK3CA, FAT1, FAT4, and CTNNB1 exhibit relatively similar mutation frequencies across both cancers, though slightly higher in SC for PIK3CA and FAT1/FAT4." (PMID 41419500, 2025). "Our data are in agreement with a recent study in which frequent FAT4 mutations were found in the analysis of 9 high-risk EC, consisting of 6 SC, 1 CCC, 1 G3EEC, and 1 dedifferentiated carcinoma." (PMID 39235515, 2025). "Other genes reported as cancer related in COSMIC (v98) showing high proportions of shared non-synonymous mutations were MUC16 (10 patients), FAT4 (6 patients) and CDKN2A (7 patients)." (PMID 39020404, 2024). "FAT atypical cadherin 4 (FAT4) is a cancer suppressor that was initially identified in mouse mammary epithelial cells." (PMID 39323626, 2024). "The results showed that FAT4 was significantly upregulated in 13 cancer types compared with that in the normal samples." (PMID 37735184, 2023).
cancer (continued). "Subsequently, the ONCOMINE database, which visualizes GEO data was also exhibited the expression map of FAT4 in different kinds of cancers." (PMID 35770846, 2023). "Collectively, these results suggest that FAT4 overexpression reduces PD-L1 levels in cancer cells in a β-catenin-dependent manner." (PMID 37658376, 2023). "Those prior results of FAT4 indicated its critical role in tumorigenesis in diverse cancer types but the detailed mechanism remained unclear and requires to be further investigated." (PMID 36811800, 2023). "Another group of cancer driver gene mutations commonly shared among OC patient samples was the family of FAT genes (FAT3 and FAT4)." (PMID 37446001, 2023). "Correlations among FAT atypical cadherin 4 (FAT4) expression, cancer immune characteristics, and infiltrated immune cell gene marker sets were analyzed." (PMID 37735184, 2023). "We performed a pan-cancer analysis to explore the potential mechanisms of FAT4 in 33 different tumors." (PMID 36051999, 2022). "We found that there exists a statistically positive correlation between FAT4 expression and CAFs for most cancer types, such as ACC, BLCA, and BRCA based on EPIC, MCPCOUNTER, xCell, and TIDE algorithms." (PMID 36051999, 2022). "We calculated the correlation between immune infiltration and FAT4 expression levels in various cancer types." (PMID 36051999, 2022). "FAT1, FAT3, and FAT4 are atypical cadherins and key regulators of cancer-relevant cellular processes including planar cell polarity and MST/HIPPO signaling, which regulates organ size." (PMID 33733072, 2021). "Several other cancer driver genes, such as ARID1A, FAT4, and PIK3CA, were also found to mutated in more than 10% of GC samples." (PMID 31781598, 2019). "HBV-associated HCC cell-line, SNU-387 was chosen for knockdown experiment as the expression of FAT4 in SNU-387 cells was higher than the other 4 cancer cell-lines which makes it a better candidate to study the effect of FAT4 knockdown." (PMID 31395065, 2019). "This study identifies frequent genetic alterations in cancer-related genes especially FAT4 illustrated the very high genomic complexity in HCC pathogenesis." (PMID 31395065, 2019). "By using NGS technologies, somatic mutations in several novel cancer-related genes such as ARID1A (7.53%), HNF4α (0.88%), FAT4 (4.71%) and IRF2 (1.06%) have been identified and suggested to be associated with HCC." (PMID 31395065, 2019). "But, FAT4 expression was lower in cancer tissues than adjacent normal tissues in patients with distant metastasis." (PMID 29435168, 2018). "FAT4 expression was lower in cancer tissues from group 2 patients than group 1 patients (5.12E-04±0.00097 vs. 1.17E-03±0.0013, P<0.05)." (PMID 29435168, 2018). "A second set consisted of an additional 15 cancer-related genes (Nf1, Mki67, Mllt4, Fgfr2, Ctnnb1, Fat1, Clp1, Fat4, Arid1a, Nat1, Nat2, Setd2, Impg1, Nbas and Npat)." (PMID 29925311, 2018). "Available public data showed that FAT4 expression was universally down-regulated in various human cancers." (PMID 26672766, 2016). "Interestingly, the distributions of several known cancer driver genes exhibit significant differences between cancer and normal tissues, such as FAT4, KMT2C, KMT2D, KRAS, PIK3CA, and PTEN." (PMID 39541191, 2024). "Previous studies indicate that mutations in FAT4 may contribute to the development of 24 types of cancers, while mutations in KMT2C may lead to 32 types of cancers." (PMID 39541191, 2024). "Here, we found that FAT4 strongly connected with immune score, stromal score, and microenvironment score, and correlated with infiltration of NK cells, Macrophages, and T/B cells, which considering to poor prognosis for many cancers." (PMID 35770846, 2023).
cancer (continued). "FAT4, the vertebrate FAT protein with the most sequence similarity to Drosophila Fat; there have been a few studies looking into the relationship between FAT4 and human cancers, and it has been proposed that FAT4 inhibits tumorigenesis and progression in endometrial, gastric, and colorectal cancers." (PMID 37658376, 2023). "Furthermore, FAT4 mRNA expression in PBMCs showed correlations with the BCLC stage; that is, patients with more advanced cancer tended to express lower mRNA levels of FAT4." (PMID 37735184, 2023). "Thus, when FAT4 is inactivated through acquired mutations, inhibition of YAP1 cell proliferation is reduced and YAP1 signaling enhances the growth and invasion of cancer cells." (PMID 37072406, 2023). "FAT4 expression was analyzed in various cancers using the TIMER database." (PMID 37735184, 2023). "Expression pattern of FAT4 in various cancers was first detected depending on TCGA‐GTEX datasets." (PMID 35770846, 2023). "In this study, we comprehensively detected FAT4 in 33 different tumors and analyzed the FAT4 expression and correlation between FAT4 expression and prognosis of cancer patients to clarify the potential molecular mechanism of FAT4 in tumorigenesis through data from the TCGA project." (PMID 36051999, 2022). "Pan-cancer analysis showed that FAT4 to be novel biomarkers for various cancers prognosis." (PMID 36051999, 2022). "Additionally, we found that the top 5 FAT4-related targeted genes were positively correlated with FAT4 in the vast majority of cancers." (PMID 36051999, 2022). "KEGG pathway analysis indicated that the role of FAT4 in the pathogenesis of cancer may be related to human papillomavirus (HPV) infection, Hippo signaling pathway, and PI3K–Akt signaling pathway." (PMID 36051999, 2022). "Interestingly, in addition to PDGFRA we found four genes previously shown to be driver mutations in different cancers: SETD2, FAT4, TRIP11 and PPP3CA (highlighted genes)." (PMID 32603362, 2020). "In our study, six non-synonymous mutations identified in FAT4 with deleterious effects on protein function were already annotated in the COSMIC database, indicating the importance of these 6 somatic mutations in cancer development." (PMID 31395065, 2019). "Notably, two trunk genes (SPEN and ITK), a branch gene (SMARCE1), and several private genes (FAT4, CACNA1D, ATR, RUNX1T1, TERT, and SRGAP3) were defined as cancer-associated genes, according to the cancer gene census." (PMID 28716121, 2017). "Therefore, FAT4 can be used as a potential prognostic biomarker for various cancers prognosis." (PMID 36051999, 2022). "Therefore, we speculated that FAT4 may has an anti-cancerous function in the proliferation and metastasis of some cancers, and regulating FAT4 expression may become one of the new directions of cancer treatment." (PMID 33063118, 2020). "In summary, FAT4 and RPL37P1 play important roles in reprogramming the TME and have the potential to become a cancer prognostic marker and therapeutic target for C1 subtype." (PMID 41019085, 2025).